ENSG00000251605 (NADH dehydrogenase )
Diseases named in the same sentence as ENSG00000251605 in open-access papers (continued):
Sharing a sentence is not in itself a finding about the gene and the disease.
cancer (22 papers, 2010 to 2025). A tumor composed of atypical neoplastic, often pleomorphic cells that invade other tissues. "In the future, the adequacy of the prediction of pathogenicity used here should be confirmed by examining the influence of each missense mutation in cancer cells on complex I (NADH dehydrogenase) activity and ROS generation." (PMID 29138417, 2017). "MtDNA sequencing revealed loss-of-function mutations in NADH dehydrogenase subunits, highlighting the role of deregulated metabolism in this and other cancers." (PMID 25859550, 2015). "Cancer cells have more mutations in their mitochondrial DNA (mtDNA) than do normal cells, and pathogenic mutations in the genes encoding mitochondrial NADH dehydrogenase (ND) subunits have been found to enhance the invasive and metastatic ability of various tumour cells in animal experiments." (PMID 29138417, 2017). "NAD+ regeneration by mitochondrial complex I NADH dehydrogenase is important for cancer cell proliferation." (PMID 39873399, 2025). "The observed increase in NADH dehydrogenase expression aligns with broader metabolic shifts that enable resistance across multiple cancer types." (PMID 41360907, 2025). "Recent research evidence has revealed that lncRNA ZFAS1 can encode a small peptide to down-regulate NADH dehydrogenase expression (NDUFA6, NDUFB11 and NDUFB4) to enhance ROS production, thus promoting cancer development." (PMID 34888249, 2021). "In this study, we report that in human cancer cells, metformin inhibits mitochondrial complex I (NADH dehydrogenase) activity and cellular respiration." (PMID 24843020, 2014). "Importantly, the anti-cancer effects of Complex I inhibitors were abolished when the inhibitor-resistant Saccharomyces cerevisiae NADH dehydrogenase NDI1 was overexpressed, proving that Complex I assists cancer by providing NAD+." (PMID 38526218, 2024). "Finally, we found that the experimentally validated translated lncRNA ZFSA1 promoted cancer cell migration by elevating cellular ROS production via the expression downregulation of NADH dehydrogenase expression (NDUFA6, NDUFB4, and NDUFB11)." (PMID 31781169, 2019). "The accumulation of NADH in cancer cells may inhibit NADH-dehydrogenase, thus decreasing α-ketoglutarate oxidation." (PMID 30551591, 2018). "Our results suggest that the NADH dehydrogenase activity of regenerating NAD+ maintains SIRT activity and suppresses antiproliferative p21Cip1 expression in cancer cells." (PMID 39873399, 2025). "Down-regulate NADH dehydrogenase expression (NDUFA6, NDUFB4, and NDUFB11) to enhance ROS production and thus promote cancer cell migration." (PMID 34888249, 2021). "In PA28 overexpressing cancer cell model 3-BrPA application harmed mitochondrial NADH dehydrogenase activity mildly and significantly failed to inhibit lactate production." (PMID 32948135, 2020). "Thus, the low rates of the State 3 oxidation of glutamate and citrate in cancer mitochondria were not caused by low activity of the ATP/ADP carrier, ATP synthase, or activities of Complexes III and IV, but rather, by low activity of Complex I (NADH dehydrogenase)." (PMID 23951286, 2013).
tumor (12 papers, 2014 to 2025). "The NDUFA13 gene encodes a NADH dehydrogenase enzyme, a part of the electron transport chain in mitochondria that can function as a tumour suppressor (Pinto and Máximo, 2018)." (PMID 37529293, 2022). "Previous study showed that mitochondrial ND6 (mitND6) gene missense mutation resulted in NADH dehydrogenase deficiency and was associated with tumor metastasis in several mouse tumor cell lines." (PMID 25934296, 2015). "On the one hand, S100A4 promotes tumor progression by up-regulating mitochondrial complex I subunit NADH dehydrogenase (ubiquinone) Fe-S protein 2 to enhance invasion and metabolic reprogramming." (PMID 40853920, 2025). "Tumor cells critically depend on mitochondrial Complex I (NADH dehydrogenase) activity to sustain NAD+/NADH balance and tricarboxylic acid (TCA) cycle functionality." (PMID 41514605, 2025). "Thus, as already applied for mitochondrial diseases, we propose NDI1 as a useful tool to uncover NADH dehydrogenase inhibition in specific tumor cells and bypass it in order to assess its potential contribution to neoplastic transformation." (PMID 35393510, 2022). "These compounds have various bioactivities, such as broad-spectrum antimicrobial activity, anti-trichomonas, anti-tumor, and inhibitory activities against H+/K+-ATPase, mitochondrial oxidative phosphorylation, NADH dehydrogenase, and phospholipase C, while they also have a little toxicity." (PMID 31671653, 2019).
infection (6 papers, 2012 to 2023). The state of being infected such as from the introduction of a foreign agent such as serum, vaccine, antigenic substance or organism. "However, PmCQ2 infection also caused reduction of all NADH dehydrogenase subunits (ND1~ND6), implying the oxidative phosphorylation of chicken was impaired, which was unfavorable to M2 macrophage activation." (PMID 32851030, 2020). "Additionally, serum mtDNA release (indicating NADH dehydrogenase activity and cytochrome c oxidation) was 1.5- to 2-fold higher in patients with rt269I infection than in patients with rt269L infection." (PMID 36997871, 2023). "NQR is the ion-pumping NADH dehydrogenase that requires the least amount of iron for its assembly (1 or 2 atoms per molecule), which could allow an active bioenergetic metabolism and cell survival during infection, in particular when the immune response has been mounted." (PMID 32324772, 2020). "Our results show that a defective NADH dehydrogenase activity leads to an increase in the NADH/NAD+ ratio and a depletion of NAD(H) intracellular pools, which is known to exert a bactericidal effect during infection." (PMID 38032200, 2023).
neurodegenerative disease (5 papers, 2015 to 2024). A disorder of the central nervous system characterized by gradual and progressive loss of neural tissue and neurologic function. "In contrast, the downregulation of NADH dehydrogenase subunit genes such as nd4 can be associated with neurodegenerative disease." (PMID 37367494, 2023). "It has been shown that neoechinulin A inhibits SIN-1-induced activation of caspase-3-like proteases and increases NADH-dehydrogenase activity, which helps to prevent neuronal cell death in neurodegenerative diseases." (PMID 38792694, 2024).
metabolic disorders (3 papers, 2014 to 2024). "Because NADH dehydrogenase is central to energy production in the cell, its malfunction may result in a wide range of metabolic disorders." (PMID 25153900, 2014).
psychiatric disorder (2 papers, 2025). A disorder characterized by behavioral and/or psychological abnormalities, often accompanied by physical symptoms. "Moreover, mutations in MT-ND6 and MT-ND5, both components of NADH dehydrogenase, have been associated with various psychiatric disorders." (PMID 40495250, 2025).
neurological diseases (1 paper, 2023). "Mutations in subunits of the mitochondrial NADH dehydrogenase cause mitochondrial complex I deficiency, a group of severe neurological diseases that can result in death in infancy." (PMID 37399212, 2023).
ENSG00000251605 also shares sentences with these, for which no sentence is quoted: depression (3 papers); mitochondrial disease (3); adenocarcinoma (2); metabolic syndrome (2); migraine (2); mitochondrial myopathies (2); Parkinson (2); type 2 diabetes (2); acute myocardial infarction (1); adenoma (1); alcoholic fatty liver disease (1); asthma (1); Ataxia (1); atherosclerosis (1); bacteremia (1); cardiovascular disease (1); carotid atherosclerosis (1); Cerebral ischemia (1); cholangiocarcinoma (1); congenital heart disease (1); dementia (1); diabetic cardiomyopathy (1); Dystonia (1); Encephalopathy (1); hematological disease (1); hereditary optic neuropathy (1); Huntington disease (1); Hyperglycemia (1); Hypertension (1); hypertrophic cardiomyopathy (1).
A further 16 diseases each share a sentence with ENSG00000251605 in 1 paper.